DYRK1A (dual specificity tyrosine phosphorylation regulated kinase 1A)
Diseases named in the same sentence as DYRK1A in open-access papers (continued):
Sharing a sentence is not in itself a finding about the gene and the disease.
lung carcinoma (8 papers, 2019 to 2023). "In 2 additional independent genome-wide CRISPR screens in Calu-3 human immortalized lung cancer cells, DYRK1A was also identified as a top proviral gene for SARS-CoV-2." (PMID 37310920, 2023). "Our data showed that high levels of DYRK1A might be related to poor overall survival in patients with lung cancer, and the DYRK1A inhibitor harmine could suppress the proliferation of NSCLC cells." (PMID 31454149, 2019). "In our study, high DYRK1A expression was observed in tumour samples from patients with lung cancer compared with normal lung tissues, and the high levels of DYRK1A were related to a reduced survival time in patients with lung cancer." (PMID 31454149, 2019). "Indeed, a weaker DYRK1A expression was correlated with a worse overall survival in breast cancer patients and a poorer prognosis in CRC and GBM patients, whereas more DYRK1A was associated with a reduced survival time in patients with lung cancer." (PMID 32751160, 2020). "Conversely, DYRK1A and DYRK1B increases chemoresistance in gastric, ovarian, breast, and lung cancers." (PMID 33804169, 2021). "Furthermore, DYRK1A and Mcl-1 proteins showed co-localization in NSCLC cells and co-expressed in tumor samples from lung cancer patients, revealing that Mcl-1 may be a novel DYRK1A substrate." (PMID 32587776, 2020). "Furthermore, DYRK1A mediated proteasome-dependent degradation of Mcl-1 in NSCLC cells, and DYRK1A co-localized with Mcl-1 in NSCLC cells and was co-expressed with Mcl-1 in tumor samples from lung cancer patients, suggesting that Mcl-1 may be a novel DYRK1A substrate." (PMID 32587776, 2020).
breast carcinoma (7 papers, 2014 to 2024). "While DYRK1A has a low mutational count in breast cancer (only 2.5% amplification mutations), these patients (altered group) mostly exhibit aggressive tumors (histological grade 2 and 3) with ER-/PR- status and are more likely categorized as patients who received chemotherapy." (PMID 38839871, 2024). "We further assessed the DYRK1A status in breast cancer using the Breast Cancer (METABRIC, Nature 2012 & Nat Commun 2016) data set from cBioportal." (PMID 38839871, 2024). "To start address this, we examined DYRK1A expression in the different molecular subtypes of breast cancer." (PMID 38839871, 2024). "First, we found DYRK1A expression to be significantly upregulated in metastatic breast cancer, compared to normal breast tissues." (PMID 38839871, 2024). "We found that DYRK1A is essential for keeping colon and breast cancer cells in the G0 quiescence state." (PMID 38839871, 2024). "We further found that inhibition of DYRK1A activity or expression decreased cell growth in vitro and reduced tumorigenesis and metastasis in vivo, using preclinical models of colon and breast cancers." (PMID 38839871, 2024). "Altogether, these results indicate that blocking DYRK1A expression releases cells from quiescence to enter G1/S but prevents or delays entry to the G2/M phase of the cell cycle in both colon and breast cancer cells." (PMID 38839871, 2024). "Our results show that DYRK1A inhibition, by means of gene silencing and pharmacological inhibition have strong impact in reducing the metastatic spread of both colon and breast cancer cells from the primary tumor to distant organs." (PMID 38839871, 2024). "Interestingly, as shown in, suppressing DYRK1A gene expression strongly and significantly reduced the number of metastatic lung nodules, suggesting that DYRK1A plays an important role during the metastatic process in breast cancer." (PMID 38839871, 2024). "In other types of solid tumors, such as breast cancer, the role of DYRK1A remains unclear." (PMID 38839871, 2024). "In addition, diazoxide, a potassium channel opener, inhibits dual specificity tyrosine-phosphorylation-regulated kinase 1A (DYRK1A), an interleukin-1 receptor-associated kinase 1 (IRAK1), and threonine and tyrosine kinase (TTK) expression in breast cancer cell lines." (PMID 37370809, 2023). "DYRK1A-KO and NT-KO control colon cancer (HCT-116) and breast cancer (MDA-MB-231) cells were serum starved for 24 h to induce quiescence before being processed with the PyroninY/Hoechst 33342 double staining." (PMID 38839871, 2024). "Findings have shown that DYRK1A and DYRK2 inactivated NFATc by phosphorylation, which increased invasive ability of breast cancer cells and drug resistance of leukemia cells." (PMID 24901999, 2014). "Interestingly, we further found DYRK1A expression to be highly upregulated in triple negative breast cancer (TNBC), the most aggressive form of the disease, compared to other breast cancer molecular subtypes." (PMID 38839871, 2024). "Our study showed REST could directly bound to DYRK1A promoter, initiating the transcription, and previous research proved REST was an tumor suppressor in breast cancer cells." (PMID 24901999, 2014). "In addition, we found that the RNAi‐mediated downregulation of MYC reduced the growth suppressive effect of T‐025 in MYC‐amplified SK‐BR3 or MCF7 breast cancer cell lines, whereas the depletion of DYRK1A did not reduce the effect of T‐025." (PMID 29769258, 2018).
colorectal cancer (7 papers, 2014 to 2024). A primary or metastatic malignant neoplasm that affects the colon or rectum. "Our previous work showed that DYRK1A is upregulated in late tumor stages and its expression is associated with bad prognosis in colorectal cancer." (PMID 38839871, 2024). "Our results showed that among DYRKs, only DYRK1A was upregulated significantly in late tumor stages, and it is associated with poor prognosis for colorectal cancer patients." (PMID 35454940, 2022). "Interestingly, we recently found that expression of DYRK1A is associated with bad prognosis and poor clinical outcome in colorectal cancer patients, strongly suggesting a role for this kinase in colon cancer formation and/or progression." (PMID 38839871, 2024). "For example, one study showed that OIP5-AS1 reduced clonogenic survival and induced apoptosis in colorectal cancer cells after irradiation via targeting miR-369-3p and DYRK1A, suggesting that OIP5-AS1 enhances radio-sensitivity in colorectal cancer." (PMID 35756672, 2022). "OIP5-AS1 was reported to participate in the regulation of radio-resistance of colorectal cancer cells by interacting with miR-369-3p and DYRK1A." (PMID 33092644, 2020). "AP4 was reported to be strongly expressed in colorectal carcinomas and repress the transcription of DYRK1A in coordinate with geminin." (PMID 24901999, 2014). "Additionally, LncRNA OIP5-AS1 was reported to regulate radio resistance by targeting DYRK1A via miR-369-3p in colorectal cancer cells." (PMID 31337985, 2019). "Both OIP5‐AS1 and DYRK1A were discovered to be downregulated in radioresistant colorectal cancer cells, and OIP5‐AS1 indirectly upregulates DYRK1A expression via miR‐369‐3p binding and suppression, resulting in the reduction of colorectal cancer cell viability." (PMID 35040588, 2022).
memory impairment (7 papers, 2015 to 2025). "We postulate the DYRK1A protein is upregulated in neurons throughout the hippocampus and is causal to memory impairments." (PMID 40078964, 2025). "DYRK1A is a protein kinase extensively studied for causing learning/memory impairment when overexpressed." (PMID 25793384, 2015). "Dyrk1a is an important candidate protein for involvement in the learning and memory impairment seen in DS patients, but the regulatory pathways impaired by DYRK1A trisomy have yet to be identified." (PMID 35914814, 2022). "In DS patients, the high activity of the DYRK1A protein kinase is inhibited, leading to the overexpression of the DYRK1A protein, which affects neuronal plasticity, resulting in cognitive abnormalities and memory impairment." (PMID 39336708, 2024). "We have previously demonstrated the neuroprotective effects of the DYRK1A inhibitor L41 (IC50=10–60 nM) on Aβ25-35-induced toxicity in mouse brains, notably preventing the onset of memory impairments and of oxidative stress, both in terms of ROS accumulation and increased peroxidised lipids." (PMID 29215943, 2018).
Anxiety (6 papers, 2017 to 2025). Intense feelings of nervousness, tension, or panic often arise in response to interpersonal stresses. "Thus, overexpression of Dyrk1A may contribute to the reduced anxiety and learning and memory deficit in Ts65Dn mice." (PMID 28377597, 2017). "Treatment with Dyrk1A inhibitor, green tea flavonol epigallocatechin-gallate (EGCG), from gestation to adulthood suppressed 3R-tau expression and rescued anxiety and memory deficits in Ts65Dn mouse brains." (PMID 28377597, 2017). "Treatment with Dyrk1A inhibitor EGCG suppressed 3R-tau expression and attenuated anxiety and memory deficits in Ts65Dn mice." (PMID 28377597, 2017).
cardiac hypertrophy (6 papers, 2013 to 2024). "Conversely, inhibition of DYRK1A or cardiomyocyte-specific deletion of the Dyrk1a gene leads to increased cardiomyocyte proliferation and cardiac hypertrophy in adult mice." (PMID 38266108, 2024). "On the other hand, DYRK1A prevents cardiac hypertrophy in vitro by inhibiting myocardial NFAT signaling in cardiomyocytes." (PMID 35126461, 2021). "Future research will show whether downregulation or overexpression of Dyrk1a is a beneficial tool in the treatment of cardiomyopathies as excess Dyrk1a appears to be useful in preventing maladaptive remodeling due to cardiac hypertrophy." (PMID 36012629, 2022). "Although these changes have been shown to occur in cardiomyocytes involved in myocardial hypertrophy, the present research constitutes the first demonstration of TRPA1-associated DYRK1A changes in CFs and the involvement of these CFs in MI-related CMF transdifferentiation." (PMID 31217840, 2019). "On the other hand, the downregulation of DYRK1A impacts the NFAT transcription factor, which induces cardiomyocytes and cardiac hypertrophy." (PMID 36012629, 2022). "Moreover, other molecules that are overexpressed in DS patients and are also related with cardiac hypertrophy could unveil similar questions: Are the elevated expression levels of DYRK1A, RCAN3 and DSCAM-AS1 involved in the cardiac hypertrophic response prevention observed in DS individuals?" (PMID 35126461, 2021). "While the extent of protein expression of DYRK1A, which has recently been identified to be a negative regulator of cardiac hypertrophy, was not changed in our transgenic model, we observed a concomitant upregulation of DYRK2 in animals overexpressing eIF2Bε." (PMID 24023715, 2013).
cognitive decline (6 papers, 2021 to 2025). "The gene for DYRK1A is found to be located within DSCR on human chromosome 21, and studies revealed that upregulation of DYRK1A is the key factor responsible for cognitive decline in patients of AD and DS." (PMID 35208955, 2022). "Inhibition of DYRK1A hyperactivity in AD by quercetin in the brain may pave the way for therapies on cognitive decline in AD patients." (PMID 36081896, 2022). "Similarly, our results in humans also indicate an age-dependent increase of plasma DYRK1A levels, which might be protective for aging and cognitive decline." (PMID 37015911, 2023).
hepatocellular carcinoma (6 papers, 2021 to 2024). A malignant tumor that arises from hepatocytes. "Interestingly, overexpression of the closely related kinase DYRK1A has recently been shown to induce EMT of hepatocellular carcinoma cells." (PMID 39482615, 2024). "Then, to check whether the regulation of Cys4p by Yak1p is conserved in mammalian cells, we tested the effect of the expression of DYRK1A in the human hepatoma HepG2 cell line." (PMID 36711154, 2022).
insulinoma (6 papers, 2017 to 2023). "Third, gene mutations in insulinomas and other tumors are permanent and irreversible; this contrasts to small molecule DYRK1A inhibitor treatment, which is envisioned as transient for months or years until the desired endpoint is achieved." (PMID 34335466, 2021). "Next, we determined the expression of DYRK1A in insulinoma MIN6 cells, and the effect of selected inhibitors was investigated by flow cytometry, confocal microscopy, and qPCR analysis." (PMID 37195917, 2023). "In our own studies, we and others have shown that NFATs do indeed translocate to the nucleus in response to DYRK1A inhibitors, and also appear to play a central role in insulin gene expression in human insulinomas." (PMID 35700053, 2022). "We confirm that DYRK1A is expressed in murine insulinoma cells MIN6." (PMID 37195917, 2023). "To address whether the transcriptional signature of β-cell replication observed in mice is modeled on replication process of human pancreatic β-cells, we compared to human insulinoma, Dyrk1a inhibitor-induced β-cell replication, and juvenile human islets." (PMID 33294783, 2020). "Finally, we highlight that previously reported mitogenic targets of the harmine class of beta cell mitogenic drugs—DYRK1A (from the red module), and MYC (also upregulated in insulinomas) and its inhibitor, MNT —are also present in this analysis." (PMID 28974674, 2017). "Thus, human insulinomas correctly predicted both SMAD and cAMP signaling might partner with DYRK1A inhibition to enhance human beta cell proliferation." (PMID 34335466, 2021).
myocardial infarction (6 papers, 2019 to 2025). Gross necrosis of the myocardium, as a result of interruption of the blood supply to the area, as in coronary thrombosis. "Based on these findings, we tested the DYRK1A inhibitor Leucettinib-92 (LCTB-92) in a mouse model of ischemia-reperfusion (I/R) myocardial infarction (MI), where it improved heart function and increased cardiomyocyte cycling." (PMID 40901489, 2025). "This study explored the role and mechanism of dual-specificity tyrosine regulated kinase 1A (DYRK1A) in regulating cardiomyocyte cell cycle activation and cardiac repair after myocardial infarction (MI)." (PMID 35810562, 2022).
Obesity (6 papers, 2018 to 2024). Accumulation of substantial excess body fat. "This could be explained in part because DYRK1A specifically inhibits GSK3β, a transcription factor associated with adiposity and obesity." (PMID 32733190, 2020). "If these beneficial effects prove to occur with all DYRK1A inhibitors, this may further enhance enthusiasm for harmine or other DYRK1A inhibition for T2D and obesity." (PMID 34335466, 2021). "The existing data suggest that the sole overexpression of DYRK1A does not reproduce peripheral phenotypes associated to obesity, such as fat accumulation and insulin deficiency, in DS humans." (PMID 32733190, 2020). "Considering that Dyrk1A is triplicated in DS, the reinforced positive NPY feedback mediated by Dyrk1A could contribute to the increased energy intake observed DS models and obesity in DS." (PMID 32733190, 2020). "Accordingly, Dyrk1A haploinsufficiency in mice produces severe glucose intolerance, hyperglycemia, hypoinsulinemia, and obesity, but without insulin resistance on a regular diet." (PMID 35681432, 2022).
frontotemporal lobar degeneration (5 papers, 2019 to 2025). "The higher levels of DYRK1A expression found in the brains of people with AD and Pick's disease and the overlap with hyperphosphorylated tau suggest that the kinase is contributing to tau disease pathogenesis." (PMID 31267651, 2019). "DYRK1A-driven tau pathology contributes to neurodegeneration not only in AD but also in other tauopathies, including Pick’s disease (PiD), progressive supranuclear palsy (PSP), corticobasal degeneration (CBD), and frontotemporal dementia (FTD)." (PMID 41189746, 2025).
head and neck squamous cell carcinoma (5 papers, 2016 to 2024). A squamous cell carcinoma that arises from any of the following anatomic sites: lip and oral cavity, nasal cavity, paranasal sinuses, pharynx, larynx, and salivary glands. "A more recent study shows that inhibition of DYRK1A decreased phosphorylation of FOXO3 on Ser253 by downregulation of AKT activity in head and neck squamous cell carcinoma cell lines." (PMID 33316942, 2020).
Huntington disease (5 papers, 2019 to 2024). Huntington disease (HD) is a rare neurodegenerative disorder of the central nervous system characterized by unwanted choreatic movements, behavioral and psychiatric disturbances and dementia. "Both Dyrk1A increased expression or its reduced expression are cumulatively reported to be associated with neuropathologies in various neurological diseases such as Down Syndrome (DS), Alzheimer’s Disease (AD), Huntington’s Disease (HD), and autistic spectrum disorder (ASD)." (PMID 39725709, 2024). "The upregulated level of DYRK1A is believed to participate in the etiology of neurodegenerative disorders, including Alzheimer’s disease (AD), PD, and Huntington’s disease (HD)." (PMID 31572127, 2019).
hyperhomocysteinemia (5 papers, 2009 to 2023). A serious metabolic condition caused by mutations in the MTHFR gene, medications, or nutritional deficiency. "Hyperhomocysteinemia is associated with low DYRK1A levels in the periphery and with a change in inflammatory status." (PMID 37015911, 2023). "We previously found a deleterious effect of hyperhomocysteinemia on expression of DYRK1A, a Down-syndrome-associated kinase." (PMID 19844572, 2009). "As we found a negative correlation between plasma Hcy levels and hepatic DYRK1A expression which underlines the effect of hyperhomocysteinemia on DYRK1A expression, we decided to analyze the over-expression of DYRK1A on Hcy metabolism." (PMID 19844572, 2009). "On the one hand, we recently reported a reduction of Dyrk1a protein level in liver of CBS-deficient mice, a murine model of hyperhomocysteinemia, suggesting a link between DYRK1A related pathways and the Hcy cycle." (PMID 19844572, 2009). "We here use a hepatocyte-specific recombinant adeno-associated viral (AAV) serotype 8-mediated DYRK1A gene therapy (AAV2/8-DYRK1A) to analyze the effect of hepatic Dyrk1A gene transfer on some altered molecular mechanisms in brain of mice with intermediate hyperhomocysteinemia." (PMID 30172984, 2018). "Liver treatment with an adenovirus expressing Dyrk1A normalizes hepatic DYRK1A level and decreases hyperhomocysteinemia in mice with hyperhomocysteinemia." (PMID 37015911, 2023). "We previously demonstrated that specific liver treatment with an adenovirus expressing Dyrk1A normalizes hepatic DYRK1A level and decreases hyperhomocysteinemia in mice with moderate to intermediate hyperhomocysteinemia." (PMID 30172984, 2018). "Moreover, in other mouse models with hyperhomocysteinemia-induced increased liver DYRK1A, brain DYRK1A levels are decreased." (PMID 37015911, 2023). "We previously observed a negative correlation between plasma Hcy levels and hepatic DYRK1A expression, which emphasizes the effect of hyperhomocysteinemia on DYRK1A expression." (PMID 19844572, 2009).
Neurodevelopmental delay (5 papers, 2008 to 2025). "Considering that DYRK1A haploinsufficiency is associated with reduced brain size and neurodevelopmental delays in human and in mice, reducing DYRK1A activity below the physiological levels would suggest deleterious effects for neurodevelopment." (PMID 30332747, 2018).